ARHGAP6 (Rho GTPase activating protein 6)
Description:
GTPase activator for the Rho-type GTPases by converting them to an inactive GDP-bound state. Could regulate the interactions of signaling molecules with the actin cytoskeleton. Promotes continuous elongation of cytoplasmic processes during cell motility and simultaneous retraction of the cell body changing the cell morphology.
Synonyms: RHOGAP6; rhoGAPX-1
Tractability: PROTAC: its protein half-life has been measured.
Gene: Protein-coding gene on chromosome X (11,117,651 to 11,665,920, reverse strand). Ensembl gene ENSG00000047648.
Subcellular location: Cytoplasm
Subcellular location (Human Protein Atlas): Cytosol; Mitotic spindle
Pathways (Reactome):
Signal Transduction: RAC3 GTPase cycle; RHOA GTPase cycle
Gene Ontology:
Molecular function: protein binding; GTPase activator activity
Biological process: negative regulation of focal adhesion assembly; negative regulation of stress fiber assembly; actin filament organization; actin filament polymerization; regulation of small GTPase mediated signal transduction; Rho protein signal transduction; positive regulation of intracellular signal transduction; signal transduction
Cellular component: cytoplasm; cytosol; actin cytoskeleton; actin filament
Homologues: Orthologues: chimpanzee ARHGAP6 (99% identical), macaque ARHGAP6 (98% identical), mouse Arhgap6 (86% identical), rat Arhgap6 (85% identical), dog ARHGAP6 (66% identical), tropical clawed frog arhgap6 (65% identical), zebrafish ARHGAP6 (38% identical), Caenorhabditis elegans rga-6 (22% identical), Drosophila melanogaster RhoGAP102A (22% identical). Paralogues in human: ARHGAP36 (20% identical).
Diseases named in the same sentence as ARHGAP6 in open-access papers:
ARHGAP6 is named in the same sentence as 24 diseases in open-access papers, as found by Europe PMC text mining. Sharing a sentence is not in itself a finding about the gene and the disease. The quoted sentences say what the papers report.
microphthalmia (2 papers, 2013 to 2017). Congenital or developmental anomaly in which the eyeballs are abnormally small. "Recently, dysfunction of RhoGAPX-1 and ARHGAP6 has been implicated in a wide range of developmental defects seen in microphthalmia with linear skin defects syndrome, while srGAP1, srGAP2, and srGAP3 have been linked to mental retardation, schizophrenia, and seizures." (PMID 28384650, 2017). "Here we report the first familial cases in which unilateral microphthalmia with linear skin defects in the mother and isolated microphthalmia in the daughter are caused by a microdeletion spanning the entire HCCS gene and part of ARHGAP6." (PMID 23401659, 2013). "In conclusion, we report on a family with two cases of unilateral microphthalmia of whom only one showed scars of neonatal linear skin lesions with a 185–220 kb microdeletion containing HCCS and ARHGAP6, supporting the hypothesis that HCCS is a candidate gene for severe eye malformations." (PMID 23401659, 2013).
Amyloid (1 paper, 2025). "Amyloid plaque burden was found to be significantly associated (P < 4.39 × 10−4) with methylation changes in FRMPD4, ARHGAP6 (in the FRMPD4 locus), and DMD." (PMID 39633006, 2025).
autoimmune disease (1 paper, 2021). A disorder resulting from loss of function or tissue destruction of an organ or multiple organs, arising from humoral or cellular immune responses of the individual to their own tissue constituents. "Moreover, the expression of other Yaa locus genes, such as male-specific lethal-subunit 3 (Msl3), Rho GTPase activating protein 6 (Arhgap6), and transcription elongation factor A (SII) N-terminal (Tceanc) was significantly increased with the progression of autoimmune disease." (PMID 34367133, 2021).
bladder cancer (1 paper, 2017). "Arhgap6 and Slc14a1 have not been implicated in breast cancer but have been implicated in a number of other cancers including cervical, endometrial, prostate and bladder cancer." (PMID 28423599, 2017).
breast carcinoma (1 paper, 2017). "Interestingly, bevacizumab, an antibody that inhibits VEGFA function and thus angiogenesis, altered the expression of Vldlr in basal-like breast cancer and Arhgap6 in endometrial cancer." (PMID 28423599, 2017).
cervical carcinoma (1 paper, 2019). A carcinoma arising from either the exocervical squamous epithelium or the endocervical glandular epithelium. "ARHGAP6 may act as a tumor suppressor by inhibiting cell proliferation, migration, invasion, and adhesion of cervical carcinoma." (PMID 30909962, 2019).
Gillespie syndrome (1 paper, 2016). "Direct sequencing of the coding exons and essential splice sites of PHF21A and ARHGAP6 revealed only polymorphic variants in the 10 individuals with Gillespie syndrome who lacked a detectable chromosomal abnormality at these loci." (PMID 27124303, 2016).
lung carcinoma (1 paper, 2021). "The upregulation of Arhgap6 gene is critically important in preventing and treating lung cancer through the suppression of matrix metalloproteinase−9 (MMP9) and vascular endothelial growth factor (VEGF)." (PMID 34367133, 2021).
melanoma (1 paper, 2020). A malignant, usually aggressive tumor composed of atypical, neoplastic melanocytes. "The cell cycle and taste transduction gene sets were enriched in high-expression groups of ARHGAP6 and ADAMTS15, respectively, whereas primary immunodeficiency and melanoma were enriched in the CHRD and SPOCK1 high-expression groups, respectively." (PMID 32218218, 2020).
neuroblastoma (1 paper, 2019). Neuroblastoma (NB) is the most common solid, extracranial childhood tumor. "The ARHGAP6 variation is different from the ones previously reported in neuroblastoma." (PMID 31452835, 2019).
tumor (9 papers, 2017 to 2024). "CHAC1 is a downstream effector of several key signaling pathways, including the RhoA-ROCK1 and p38 MAPK pathways, which are modulated by tumor suppressors like ARHGAP6." (PMID 39534397, 2024). "Another investigation showed that low expression of ARHGAP6 is linked to increased metabolic activity in NSCLC, which confirms that ARHGAP6 is a potential tumor suppressor in NSCLC." (PMID 37190124, 2023). "GS tumours show RAS homologue gene family, member A (RHOA) and E-cadherin (CDH1) gene mutations and the Claudin-18 (CDLN18)-Rho GTPase activating protein 6/26 (ARHGAP6/26) translocation." (PMID 31235864, 2019). "Similarly, we found that eRNAs chr19.53635063.53635358 and chrX.11360130.11360328 were downregulated and located near ZNF415 and ARHGAP6, which have been identified as tumor-suppressor genes." (PMID 34439379, 2021). "Overexpression of ARHGAP6, which inhibits these pathways, results in increased CHAC1 expression, thereby promoting ferroptosis and inhibiting tumor growth." (PMID 39534397, 2024). "Other RhoGAPs, such as ARHGAP4, ARHGAP6, ARHGAP9, ARHGAP12 and ARHGAP25, have also demonstrated tumor suppressor roles in different types of tumors 26-30." (PMID 36168627, 2022). "Conversely, eRNAs chr19.53635063.53635358 and chrX.11360130.11360328 were found to be located near the tumor-suppressor genes ZNF415 and ARHGAP6." (PMID 34439379, 2021). "Therefore, Vldlr and Arhgap6 may also impact tumor angiogenesis in our model." (PMID 28423599, 2017). "The NetMHCpan 4.0 was used to predict potential peptides derived from three CLDN18-ARHGAP fusion types previously reported to be present in tumor samples, including junctions of CLDN18 (exon 5)-ARHGAP26 (exon 12), CLDN18 (exon 5)-ARHGAP26 (exon 10) and CLDN18 (exon 5)-ARHGAP6 (exon 2)." (PMID 39164472, 2024).
cancer (5 papers, 2012 to 2025). A tumor composed of atypical neoplastic, often pleomorphic cells that invade other tissues. "Noteworthy, several candidate susceptibility genes (PRKCA, BMP6, ADAMTS19, ARHGAP6, FUT9/8, FAM108C1, CHL1, BTBD9 and WDR52) are involved in the actin cytoskeleton arrangement, cell adhesion and cell motility processes, which are important for cancer invasion and metastasis." (PMID 22532847, 2012). "The other genes (SMARCE1, DISC1, CENTD2, RHOT1, ARHGAP6, ARHGEF9 and ARHGEF11) are also involved in cancer progression or chemoresistance." (PMID 23300757, 2012).
ARHGAP6 also shares sentences with these, for which no sentence is quoted: infection (2 papers); Autoimmunity (1); endometrial cancer (1); gastric cancer (1); lung adenocarcinoma (1); mental retardation (1); metabolic disease (1); Obesity (1); primary immunodeficiency (1); prostate carcinoma (1); schizophrenia (1); serous ovarian carcinomas (1).